VIM (vimentin)
Diseases named in the same sentence as VIM in open-access papers (continued):
Sharing a sentence is not in itself a finding about the gene and the disease.
breast carcinoma (continued). "On the other hand, the levels of the mesenchymal markers N-cadherin, Twist1 and vimentin were 2.3, 12 and 3 fold higher in breast cancer cells treated with SFCM from TCF-169-CHEK2-siRNA as compared to SFCM from control cells." (PMID 27484185, 2016). "This pattern of vimentin expression with associated morphological changes is also seen in another cell type: the non-invasive, hormone receptor-positive MCF-7 breast cancer cells." (PMID 27049728, 2016). "We found that AESN (200 μg/mL) markedly attenuated N-cadherin, ZEB1, and vimentin expressions in MCF-7 breast cancer cells." (PMID 27136519, 2016). "PARP3 expression is higher in breast cancer cells of the mesenchymal phenotype and correlates with the expression of the mesenchymal marker Vimentin while being in inverse correlation with the epithelial marker E-cadherin." (PMID 27579892, 2016). "Several studies examined EMT-related markers, such as Vimentin, N-cadherin, Snail, Slug, Twist, N-cadherin and cytokeratins expression, in different subtypes of breast cancer tissues by immunohistochemistry (IHC)." (PMID 26821054, 2016). "When quantified, vimentin expression was significantly decreased in all NHE1 mutant breast cancer cells (*P < 0.001, N = 3); however, the down-regulation of vimentin observed in S703A cells (+P < 0.01, N = 3) was greater than that of SSSA and 1K3R4E cells." (PMID 27049728, 2016). "Previously, using systems biology approach and cancer signaling networks, we identified top-5 highly expressed and connected proteins (HSP90AB1, CSNK2B, TK1, YWHAB and VIM) in the invasive MDA-MB-231 breast cancer cell line." (PMID 27527857, 2016). "The protein expression of E-cadherin, N-cadherin, Vimentin and Snail in the breast cancer cells subject to NC at 48 h were evaluated by Western blotting." (PMID 27313840, 2016). "Vimentin was widely expressed in breast cancer, whereas in metastatic HNSCC it was expressed only in minority of the cells and mostly in cells at the colony edge." (PMID 27075696, 2016). "The inhibition of Notch2 activation attenuated the radiation-induced invasive and migratory properties of MCF7 breast cancer cells and recovered the E-cadherin protein levels with the down-regulation of N-cadherin, vimentin and NICD2." (PMID 27462787, 2016). "Overexpression of LIF in breast cancer and colorectal cancer cells promotes cancer cells to acquire mesenchymal features, increase the expression of mesenchymal markers, including Vimentin and N-cadherin, and decrease the expression of E-cadherin." (PMID 26716902, 2016). "Further, the expression of vimentin was studied in the breast cancer tissues by immunohistochemistry." (PMID 26906973, 2016). "Accordingly, protein levels of E-cadherin were up-regulated and accumulation of N-cadherin and vimentin was abolished after knock-down of Notch2 in irradiated MCF7 breast cancer cells." (PMID 27462787, 2016). "Basal-B cells express high CD44 and CDK4, along with high levels of the mesenchymal marker vimentin, while basal-A or luminal-like breast cancer cells display higher CD24 level with a high expression level of the epithelial marker E-cadherin." (PMID 27759034, 2016). "In their study, expression of P-cadherin and Vimentin were examined by IHC in a large cohort of breast carcinomas (n = 1145)." (PMID 26821054, 2016). "There are various cancers in which over-expression of vimentin is present including breast cancer, prostate cancer, lung cancer, CNS tumors, gastrointestinal tumors, malignant melanoma and other cancer types." (PMID 27875990, 2016). "They analyzed the expression of two EMT markers, Twist and vimentin, in CTCs of breast cancer patients by immunofluorescence staining." (PMID 27529216, 2016). "An impaired upregulation of Snail and Vimentin and an inefficient downregulation of E-cadherin was also observed in the breast cancer MCF7 cells upon PARP3 silencing." (PMID 27579892, 2016).
breast carcinoma (continued). "WA has been shown to downregulate EMT markers such as Vimentin and β-catenin in breast cancer stem cells." (PMID 27447565, 2016). "EMT is an available strategy to target cancer metastasis, and the loss of E-cadherin and gain of Vimentin have been known to play vital roles in EMT process of various malignancies, breast cancer included." (PMID 27313840, 2016). "Given the radical modulation of the epithelial marker E-Cadherin found in the MDA-MB231 breast cancer sublines, we decided to analyze the expression of the mesenchymal markers N-Cadherin and vimentin." (PMID 27507057, 2016). "An RT-PCR assay was further used to show that the proportion of ALDH1 positive CTCs was higher in more advanced breast cancer patients and correlated with vimentin and fibronectin expression." (PMID 27189371, 2016). "Withaferin-A also showed dose-dependent inhibition of metastatic lung nodules and increased vimentin phosphorylation at serine-56 in a mouse model of breast cancer in vivo." (PMID 26959007, 2016). "All mammary tumors derived from p16mt;Brca1MGKO mice were stained positively for vimentin (Vim), a mesenchymal marker, and Twist, an EMT transcription factor." (PMID 27811360, 2016). "Elevated vimentin and reduced E-cadherin levels correlate with increased breast cancer cell migration, invasion, and malignant cancer phenotypes." (PMID 25749031, 2015). "Increased vimentin expression has been reported in a number of epithelial cancers, including breast cancer, lung cancer and esophageal squamous cell carcinoma." (PMID 26095281, 2015). "We found expression levels of fibronectin, p-vimentin and N-cadherin to be significantly decreased in the breast cancer cell lines after hsa-miR-195 overexpression." (PMID 26632252, 2015). "Recently, the role of Vimentin in EMT has also been reported in breast cancer cell lines, which was attributed to a mechanism involving the activation of AEG-1." (PMID 25880337, 2015). "In this study, we evaluated the role of vimentin for both the mechanic and tumorigenic approaches to breast cancer cells." (PMID 25965826, 2015). "For example, cytokeratin is downregulated and mesenchymal marker vimentin replaces cytokeratin in malignant breast cancer cells." (PMID 25965826, 2015). "Consistently, flubendazole reduced mesenchymal markers (β-catenin, N-cadherin and Vimentin) expression and induced epithelial and differentiation marker (Keratin 18) expression in breast cancer cells." (PMID 25811972, 2015). "In this study, we have clearly demonstrated a positive correlation between markers of centrosome amplification and vimentin expression in breast cancer patients." (PMID 25868856, 2015). "MDA-MB-231 breast cancer cells are reported to be more mesenchymal-like because these cells express high levels of mesenchymal markers, such as vimentin, fibronectin, and slug, whereas the epithelial marker E-cadherin was barely detectable." (PMID 25788271, 2015). "Flubendazole treated MDA-MB-231 cells exhibited the downregulation of Vimentin and upregulation of Keratin 18, indicating that flubendazole induced differentiation of breast cancer cells." (PMID 25811972, 2015). "Further analysis of EMT markers revealed that the increased expressions of Bmi-1 in breast cancer cell lines were correlated to increased expression of vimentin and decreased expression of E-cadherin." (PMID 25734775, 2015). "By analyzing the mRNA expression profiles of a publicly available dataset of a panel of breast cancer cell lines, we found that high expression of αv integrin positively correlates with expression of the mesenchymal markers Slug, N-Cadherin and Vimentin." (PMID 25849225, 2015). "The expression of EMT markers, including CDH1, CDH2, VIM, ZEB1 and ZEB2, is associated with poor prognosis of breast cancer patients." (PMID 26062653, 2015). "b E-cadherin, (c) N-cadherin, (d) vimentin expression of single stroma PGCC in human breast cancer with lymph node metastasis (Black arrow head, IHC,×200)." (PMID 26702618, 2015).
breast carcinoma (continued). "Downregulation of Slug resulted in a significant increase of E-cadherin expression and a prominent decrease of the vimentin level, and weakened the migration and invasion capacities in breast cancer cells." (PMID 25645291, 2015). "Clinical microarray results demonstrated that increased levels of vimentin mRNA after chemotherapy correlated to a poor prognosis of breast cancer patients." (PMID 25965826, 2015). "This study compared the expression of epithelial-mesenchymal transition (EMT)-related proteins, including E-cadherin, N-cadherin, and vimentin, between PGCCs and their daughter cells, and control breast cancer cell lines MCF-7 and MDA-MB-231." (PMID 26702618, 2015). "Keratin 18 is considered as a differentiation and epithelial marker, indicating differentiation and mesenchymal-epithelial transition (MET) of breast cancer cells, while Vimentin functions as a dedifferentiation and mesenchymal marker in breast cancer cells." (PMID 25811972, 2015). "For example, vimentin expression was shown to be required for the induction of AXL expression and such regulation functionally contributed to the EMT phenotype in breast cancer cells and accordingly silencing of vimentin decreased AXL levels significantly." (PMID 25337673, 2014). "By regulating RNPC1 expression, we found E-cadherin was promoted in the RNPC1 overexpression breast cancer cell lines, whereas Vimentin level was reduced." (PMID 24884756, 2014). "MiR-30 was reported to suppress the migratory ability and invasiveness of breast cancer cell lines by directly targeting vimentin." (PMID 24598126, 2014). "Vimentin is a well-documented mesenchymal marker and its over-expression results in an increase in the motility invasiveness of breast cancer cells." (PMID 24967704, 2014). "MiR-506 was reported to inhibit TGFβ-induced EMT by directly targeting vimentin in a human breast cancer cell line." (PMID 24598126, 2014). "Growth factor stimulation appears to be a part of this “crosstalk” as epidermal growth factor (EGF) leads to epitheliomesenchymal transition-like changes in human breast cancer cells including upregulation of vimentin and downregulation of E-cadherin." (PMID 25140302, 2014). "Conditioned medium from ASCs containing PDGF-D induced the mesenchymal markers fibronectin, alpha smooth muscle actin, and vimentin in breast cancer cells in vitro." (PMID 24586900, 2014). "Other data showed that more invasive breast cancer lines expressed vimentin, indicating its usefulness in identifying cases with poorer prognosis." (PMID 24527079, 2014). "Up on treatment with fluvastatin, vimentin was down regulated in MDA-MB-231 breast cancer cells by Western blot analysis." (PMID 25268751, 2014). "In human breast cancer samples, vimentin expression is found in high-grade ductal carcinomas with low ER expression levels." (PMID 25134718, 2014). "In conclusion, fluvastatin alters levels of cytoskeletal proteins, primarily targeting vimentin through increased caspase-3- mediated proteolysis, thereby suggesting a role for vimentin in statin-induced breast cancer cell death." (PMID 25268751, 2014). "In the presence of mevalonate, an immediate downstream product of HMGCoA, fluvastatin mediated down regulation of vimentin was significantly reversed, thereby suggesting a possible role for vimentin in cell survival and proliferation of breast cancer cells." (PMID 25268751, 2014). "Several studies have reported overexpression of vimentin as a marker of basal-like breast cancer cells." (PMID 25171249, 2014). "Vimentin has been found to be overexpressed in various epithelial cancers, including prostate cancer, gastrointestinal tumors, breast cancer, malignant melanoma and lung cancer." (PMID 25244643, 2014). "Our data on mesenchymal markers (i.e. vimentin and β-catenin translocation) provided evidence that epithelial cells acquire mesenchymal characteristics in a process of mineralization in breast cancer." (PMID 24758513, 2014).
breast carcinoma (continued). "Biopsy specimens were also analyzed for vimentin protein expression to analyze progression in breast cancer." (PMID 24527079, 2014). "Upregulation of vimentin has been reported in various cancers and aggressive breast cancer cell lines." (PMID 23295955, 2013). "In this study, a high-throughput RNAi screening approach was undertaken to identify novel vimentin regulators among ~600 cancer relevant genes in cultured breast cancer cells." (PMID 23295955, 2013). "Vimentin is a key regulator of breast cancer cell migration and a marker for mesenchymal subtype, characteristic of cancer cells that have undergone epithelial-mesenchymal transition." (PMID 26237148, 2013). "Here, we performed an RNA interference screen followed by protein lysate microarray analysis in bone metastatic MDA-MB-231(SA) breast cancer cells to identify novel regulators of vimentin expression." (PMID 23295955, 2013). "To reveal novel modulators for vimentin expression in breast cancer cells, we conducted two replicate RNAi screens in basal highly metastatic MDA-MB-231(SA) cells." (PMID 23295955, 2013). "TCs in primary mammary gland stromal cells with long and thin overlapping cytoplasmic processes, expressed c-kit/CD117, CD34 and vimentin in reconstitute breast cancer tissue." (PMID 23206234, 2013). "Vimentin is a key regulator of breast cancer cell migration and a marker for mesenchymal subtype, characteristic of cancer cells that have undergone epithelial–mesenchymal transition (EMT)." (PMID 23295955, 2013). "The levels of miR-7 expression was positively correlated with E-CADHERIN mRNA and negatively correlated with VIMENTIN mRNA levels in breast cancer samples." (PMID 22876288, 2012). "It has been reported that WF-A causes disruption of the vimentin network in different cell types including endothelial cells, astrocytes and vimentin positive breast cancer cell lines." (PMID 22900077, 2012). "Analysis of miR-7 as well as E-CADHERIN and VIMENTIN mRNA levels in breast cancer tissues reveals that miR-7 expression is an indicator of epithelial differentiation in breast cancer." (PMID 22876288, 2012). "E-cadherin down-regulation and Vimentin up-regulation are commonly observed in more invasive basal cancer subtypes and have been positively correlated with poor prognosis in breast cancer patients." (PMID 22952657, 2012). "Immunofluorescent assay was used to investigate the effect of miR-125b on expression and distribution of vimentin in breast cancer cell lines MDA-MB-231 and MCF-7/ADR." (PMID 22693547, 2012). "Our results demonstrated that miR-125b was a novel regulator for α-SMA and vimentin in breast cancer cells." (PMID 22693547, 2012). "Since vimentin is a cytoskeletal intermediate filament protein frequently expressed in neoplastic cells with metastatic properties, including breast cancer, it was interesting to analyze this protein as a marker of metastasis." (PMID 22754462, 2012). "The expression of the mesenchymal marker vimentin was clearly induced in the relatively well-differentiated breast cancer cells (MCF-7) co-cultured with CAFs." (PMID 23251387, 2012). "A previous study using human breast cancer cells showed that accumulation of cytoplasmic or nuclear β-catenin and vimentin expression coincide." (PMID 23216791, 2012). "AXL and VIM are up-regulated together in migrating cells at monolayer wound edges and in breast carcinomas." (PMID 22570691, 2012). "Adversely, Kindlin-1 upregulates Wnt signaling component β-catenin and EMT markers Vimentin and fibronectin in breast cancer cells." (PMID 23209705, 2012). "This signature was found to distinguish a series of breast cancer cell lines that have demonstrable, classical EMT hallmarks, including loss of E-cadherin protein and acquisition of N-cadherin and vimentin expression." (PMID 21347235, 2011).
breast carcinoma (continued). "A statistically significant correlation (Spearman's ρ analysis) was also observed between the number of CTCs expressing Twist and vimentin in early stage (P = 0.027) and metastatic (P = 0.009) breast cancer patients." (PMID 21663619, 2011). "Our study found that vimentin, although an aggressive marker for breast cancer growth, is another indicator for a favorable tumor response to chemotherapy." (PMID 22110952, 2011). "It is thought that the mechanism by which ZEB2 induces EMT is by its ability to repress the epithelial cell junction protein E-cadherin and induce the mesenchymal marker, vimentin, in breast cancer cell lines." (PMID 21303533, 2011). "The epithelial-mesenchymal transition (EMT) of breast cancer cells was analyzed by wound-healing assay and Western blot of snail, vimentin and E-cadherin expression." (PMID 22023707, 2011). "We selected five genes (CAV1, DHFR, TYMS, VIM, ZEB1) known to be associated with drug sensitivity and the epithelial-mesenchymal transition of breast cancer." (PMID 21501481, 2011). "A direct role of vimentin in cancer invasiveness, when co-expressed with keratins, was suggested in breast carcinoma cell lines." (PMID 21747928, 2011). "Among early breast cancer patients, vimentin-and Twist-expressing CK+ CTCs were identified in 77% and 73% of the patients, respectively, and in 100% of the patients with metastatic breast cancer for both markers (P = 0.004 and P = 0.037, respectively)." (PMID 21663619, 2011). "Over-expression of vimentin in breast cancer model leads to augmentation of motility and invasiveness in vitro, which can be transiently down-regulated by antisense oligonucleotides to vimentin." (PMID 21317457, 2010). "The transfection of the non-invasive human breast cancer cell line (MCF7) with vimentin gene led to accelerated invasiveness." (PMID 19695088, 2009). "Vimentin loss is associated with the invasive and mesenchymal phenotype observed following EMT in multiple breast cancer cell types." (PMID 19829710, 2009). "Ablation of vimentin expression inhibits migration and invasion of colon and breast cancer cell lines and promotes conversion of tumourigenic prostate epithelial cells into slow growing, less aggressive cells." (PMID 19367286, 2009). "Other data showed that more invasive breast cancer lines expressed vimentin, suggesting its usefulness in identifying cases with poorer prognosis." (PMID 19695088, 2009). "We were not able to better delineate an immunohistochemical definition of basal type of breast cancer by adding vimentin to the immunopanel consisted of ER, PgR, HER2, CK5/6, 14 and 17 markers, when overall survival was a primary end-point." (PMID 19695088, 2009). "Invadopodia formation and vimentin expression are correlated with Syk negativity in breast cancer cells." (PMID 19829710, 2009). "It has been reported that stem cells from human mammary glands and mammary carcinomas express EMT markers including increased vimentin, SLUG and FOXC2 gene expression and decreased E-cadherin expression." (PMID 20027313, 2009). "We show that Snail protein expression increased in breast cancer cell lines exposed to severe hypoxia (0.1%) and that expression of E-cadherin and the mesenchymal marker vimentin were also affected in some cell lines." (PMID 19844232, 2009). "In our study we checked the usefulness of vimentin expression in identifying cases of breast cancer with poorer prognosis, by adding vimentin to the immunopanel consisting of basal type cytokeratins, estrogen, progesterone, and HER2 receptors." (PMID 19695088, 2009). "It is believed that the over-expression of VIM, which is related to poor prognosis in breast cancer patients presenting with metastasis potential, results in a more invasive capacity of breast cancer cells in vitro and in vivo." (PMID 19087274, 2008).